LGR5 (leucine rich repeat containing G protein-coupled receptor 5)
Diseases named in the same sentence as LGR5 in open-access papers (continued):
Sharing a sentence is not in itself a finding about the gene and the disease.
glioma (continued). "Our results revealed that PI was positively related to LGR5 expression indicating LGR5 may be involved in cell proliferation in gliomas." (PMID 24172981, 2014). "Additionally, to investigate the function of LGR5 in glioma in vivo, siRNA-transfected and parental U87 cells were orthotopically transplanted into nude mice." (PMID 24172981, 2014). "Moreover, the LGR5 expression was determined in human glioma tissues." (PMID 30208924, 2018). "As LGR5 is not only a target gene of the Wnt signaling pathway, but is also a stem cell marker in the intestine, stomach and hair follicles in the skin, we also detected the capability of tumorsphere formation by deregulating the expression of LGR5 in a glioma cell line." (PMID 24172981, 2014). "To confirm this hypothesis, we explored the role of LGR5 in three representative glioma cell lines." (PMID 24172981, 2014). "Functionally, LGR5 has been shown to promote EMT process and metastasis in hepatocellular carcinoma, colon cancer, and glioma and to predict poor survival of glioma patients." (PMID 32382005, 2020). "In glioma, DANCR can restore LGR5 (Leucine-rich repeat-containing G protein-coupled receptor 5), PI3K, AKT, and p-AKT accumulation reduced by miR-216a, facilitating proliferation, migration, invasion, and angiogenesis and inhibited apoptosis." (PMID 31799189, 2019). "To further reveal the relationship between LGR5 and the reported CSC markers in GSCs, we obtained enriched cells (U251-GSCs, 8591-GSCs) from U251 and 8591 glioma cells (top)." (PMID 30208924, 2018). "Similar to the results of the animal experiment in vivo, LGR5 expression level was proved to be positively correlated with WHO grade, Ki67 and N-cadherin by quantitative analysis of IHC of human glioma tissues." (PMID 30208924, 2018). "Conversely, LGR5− glioma cells showed low expression of CD133, CD44, CD90, CD24, and EpCAM, while the expression of CD90 remained unchanged in LGR5+ and LGR5− glioma cells." (PMID 30208924, 2018). "TMZ is the foremost medicine for clinical adjuvant treatment of glioma; therefore, we tested the resistance of LGR5+ and LGR5− cells to TMZ." (PMID 30208924, 2018). "Significant differences in LGR5 levels were observed between high-grade (WHO III and IV) and low-grade (WHO I and II) glioma as well as between WHO I and WHO II glioma (P < 0.001, P < 0.05, respectively)." (PMID 30208924, 2018). "However, the role of LGR5 in glioma invasion remains unclear, particularly for GSCs." (PMID 30208924, 2018). "Our study demonstrates that LGR5 can serve as a functional GSC marker, drive GSCs EMT and by activating the Wnt/β-catenin pathway in vitro and in vivo, and predicts glioma recurrence and poor prognosis." (PMID 30208924, 2018). "Our data demonstrated that the expression of LGR5 as detected by immunohistology was positively and markedly correlated with increasing WHO grade in the gliomas, which is consistent with the results of a previous report." (PMID 24172981, 2014). "There were significant differences in LGR5 IRS between grade I and grade III (P<0.05), grade I and grade IV (P<0.005), and grade II and grade IV (P<0.05) gliomas, respectively." (PMID 24172981, 2014). "In view of the differences in LGR5 expression as well as the multifarious differences in high- and low-grade glioma, we divided all glioma patients into a low-grade glioma (LGG, WHO I and II) group and a high-grade glioma (HGG, WHO III and IV) group." (PMID 30208924, 2018). "The results clearly showed higher expression levels of LGR5 and N-cadherin in LGR5+ cells, suggesting that LGR5 may be related to invasiveness and EMT in glioma." (PMID 30208924, 2018). "LGR5 is a new functional GSC marker and prognostic indicator that can promote EMT by activating the Wnt/β-catenin pathway and would thus be a novel therapeutic target for glioma." (PMID 30208924, 2018). "Although LGR5 has been reported to be involved in the Wnt/β-catenin pathway, it has not been verified in glioma." (PMID 30208924, 2018).
glioma (continued). "Epigenetic regulation of LGR5 in gliomas has not yet been described." (PMID 29428975, 2018). "Moreover, the relevance of LGR5 to invasion and EMT in glioma remains unknown." (PMID 30208924, 2018). "However, the exact mechanisms of LGR5 in glioma cells have not been elucidated." (PMID 24172981, 2014).
liver cancer (19 papers, 2016 to 2025). An epithelial or non-epithelial malignant neoplasm that arises from the liver. "LSD1-associated activation of the β-catenin signaling is essential for maintaining the activity of LGR5+ liver cancer initiating cells." (PMID 40799516, 2025). "Lgr5 is associated with the activity of PTEN/AKT and Wnt/β-catenin pathways, the modulation of which changes the population of Lgr5+ cells in hepatic cancer." (PMID 38338736, 2024). "In liver cancer, leucine‐rich repeat‐containing G‐protein coupled receptor 5 (LGR5) compartment represents an important tumor‐initiating cell (TIC) population and served as a potential therapeutic target." (PMID 37578396, 2023). "Recent studies have demonstrated that LGR5 expressing population is an important TICs population in liver cancer." (PMID 37578396, 2023). "Most importantly, we discovered that LGR5+ cells were specifically depleted in experimental liver cancer models, inhibiting CAF‐mediated tumor formation, growth, and metastasis." (PMID 37578396, 2023). "It is highly expressed in patients with liver cancer and is significantly related to poor prognosis, and mediates liver cancer and apoptosis by regulating LGR5-mediated β-catenin and c-Myc signaling." (PMID 37583908, 2023). "LGR5 marks tumor-initiating cells with a cancer stem cell-phenotype in liver cancer and these cancer stem cells are thought to be responsible for tumor progression, including metastasis." (PMID 36741736, 2022). "Simultaneously targeting both compartments as demonstrated in this study by 5-FU treatment in combination with DT-mediated ablation of the LGR5+ compartment was effective in combating liver cancer in experimental models." (PMID 32327656, 2020). "A prediction would thus be that in liver cancer, the LGR5+ cells would be more resistant to anticancer treatment as compared with the LGR5− cells." (PMID 32327656, 2020). "Through a series of functional assays, in particular in vitro organoid initiation and in vivo tumor formation, we have demonstrated the importance of these LGR5 TICs in liver cancer." (PMID 32327656, 2020). "For functional comparison of LGR5+ and LGR5− liver cancer cells, we first assessed their relative clonogenic ability using an organoid initiation assay." (PMID 32327656, 2020). "Analysis of the resulting hepatic neoplasms revealed the stable presence of an LGR5+ compartment in these liver tumors." (PMID 32327656, 2020). "Our results show that in liver cancer, an LGR5+ compartment exists that is superior in tumor initiation and mediates therapy resistance." (PMID 32327656, 2020). "Although our study primarily focused on mouse models, the relevance of the LGR5+ compartment deserves to be further investigated in human liver cancer." (PMID 32327656, 2020). "Although we have demonstrated the feasibility and value of targeting LGR5 TICs in murine liver cancer, therapeutic ablation of these cells remains challenging." (PMID 32327656, 2020). "Conversely, overexpression or knock-out of LGR5 in several colon and liver cancer cell lines led to significant changes in actin cytoskeleton structures and cell–cell adhesion in the absence of RSPO stimulation." (PMID 28739799, 2017). "The function of LGR5 in cancer cells appeared to be tumor-type dependent with tumor suppressor-like activity in colon and liver cancer cells and tumor-promoting activity in other cancer cell types." (PMID 28739799, 2017). "Consequently, this study aimed to construct a three‐dimensional (3D) co‐culture organoid model of primary LGR5‐expressing tumor stem cells from primary murine liver tumors with CAFs to investigate the impact of CAFs on LGR5 marked TICs in liver cancer." (PMID 37578396, 2023). "Thus, we envision that our identification of targetable LGR5 TICs in murine liver cancer bears important implications for future therapeutic development." (PMID 32327656, 2020).
liver cancer (continued). "Similarly, we have observed that the combination of LGR5 lineage ablation with 5-FU chemotherapy can also lead to enhanced anti-liver cancer activity in mouse organoid." (PMID 32327656, 2020). "Whether an LGR5+ compartment exists in liver cancer remains obscure, and the possible importance of such a compartment in this disease is unexplored." (PMID 32327656, 2020). "We further assessed therapeutic targeting of LGR5 liver cancer cells in vivo." (PMID 32327656, 2020). "We have now observed the induction of LGR5+ from LGR5− liver cancer cells." (PMID 32327656, 2020). "This study has demonstrated that liver cancer contains an LGR5+ compartment that has various hallmarks of TICs/CSCs, including an increased capacity for tumor organoid formation in culture and allograft formation in mice, as well as resistance against conventional anticancer therapy." (PMID 32327656, 2020). "Thus, targeting the LGR5+ compartment markedly enhances the efficacy of conventional treatment aimed at combating liver cancer." (PMID 32327656, 2020). "It has been reported that PTEN-dependent AKT signaling significantly increased the number of Lgr5+ (leucine-rich repeat-containing G protein-coupled receptor 5) cells, while Wnt/β-catenin pathway inhibition suppressed their proliferation in diethylnitrosamine-induced liver cancer." (PMID 39769181, 2024). "Therefore, the interaction between CAFs and LGR5+ cells maybe closely related to the LGR5 tumor stem cell‐related liver tumor initiation or development liver cancer." (PMID 37578396, 2023). "Also, the prevention of excessive proliferation of Lgr5+ hepatocytes may provide a future treatment modality for liver cancer." (PMID 33767594, 2021). "Whether LGR5+ cells are present in liver cancer is largely unknown." (PMID 32327656, 2020). "Thus, we aimed to investigate whether LGR5 marks CSCs/TICs in liver cancer, and to explore the potential for therapeutic targeting of these cells." (PMID 32327656, 2020). "With respect to that option, it has been recently shown that murine liver cancer cells have a similar expression pattern to Lgr5 liver progenitors induced after damage, suggesting that deregulation of a Wnt‐driven regenerative response could be a factor contributing to liver cancer." (PMID 26799921, 2016). "The exceptions are liver cancer (HCC), where LGR5 expression is depressed relative to healthy tissue, and adrenal gland, oesophageal and pancreatic cancers that are not significantly different in LGR5 expression relative to healthy tissues." (PMID 39169164, 2024). "Lgr5+ constitutes a marker for CSCs within the TME and their monitoring can provide a new treatment option for liver cancer patients by targeting the PTEN/AKT and Wnt/β-catenin signaling pathways." (PMID 38612436, 2024). "This study identifies the LGR5+ compartment as an important CSC population, representing a viable therapeutic target for combating liver cancer." (PMID 32327656, 2020). "Overall, these effects of LGR5 on F-actin structure and cell adhesion in CHO and HEK293 cells are similar to the phenotypes observed with overexpression of LGR5 in colon and liver cancer cell lines." (PMID 28739799, 2017). "As the most common and functional stemness-associated pathway, β-catenin signaling was verified to be enriched in leucine rich repeat containing G protein-coupled receptor 5 (LGR5) positive and OV6+ liver cancer-initiating cells to sustain their CSCs identities." (PMID 36293184, 2022). "Supporting this hypothesis, Lgr5+ cells have been identified as tumour initiating cells in mouse liver cancer and YAP can induce liver cancer." (PMID 33732709, 2021). "Thus, we have identified the LGR5+ compartment as an important TIC population, representing a viable therapeutic target for combating liver cancer." (PMID 32327656, 2020).
liver cancer (continued). "Co-staining with hepatocyte marker (HNF4α) or cholangiocyte marker (CK19) revealed that a proportion of LGR5 cells in the tumor express HNF4α or CK19, suggesting that LGR5+ cells may give rise to both a HCC-like and a CC-like phenotype, the two main types of primary liver cancer." (PMID 32327656, 2020).
glioblastoma (17 papers, 2013 to 2025). The most malignant astrocytic tumor (WHO grade IV). "In glioblastoma the number of the LGR5 expressing cells increased with the tumor staging and correlated with poor outcome." (PMID 30770730, 2019). "Studies of human cancer cell lines have now confirmed that LGR5 promotes the growth and/or survival of colorectal and basal cell carcinoma, glioblastoma, and neuroblastoma." (PMID 23596566, 2013). "Studies have further demonstrated that Lgr5 regulates the malignant phenotype in a subset of patient-derived glioblastoma stem cells, which may represent as a potential predictive marker of glioblastoma." (PMID 31358061, 2019). "Lgr5 is also of relevance in pediatric tumors including glioblastomas and Ewing's Sarcoma." (PMID 26697427, 2015). "A transcriptomic analysis of LGR5-silenced glioblastoma stem cells showed that L1CAM is downregulated and therefore is regulated by LGR5, altough the molecular mechanism remains to be elucidated." (PMID 32429448, 2020). "More recently, LGR5 (leucine-rich repeat-containing G protein-coupled receptor 5), a novel stem cell marker of the intestinal epithelium and the hair follicle, was reported to be a poor prognostic factor in GBM and to be required for survival of glioblastoma stem-like cells." (PMID 26506620, 2015).
neuroblastoma (15 papers, 2013 to 2024). Neuroblastoma (NB) is the most common solid, extracranial childhood tumor. "The high expression of LGR5 in high-risk neuroblastoma is surprising as LGR5 is typically found in epithelial cells and fibroblasts." (PMID 39065640, 2024). "LGR5 is a stem cell marker which is highly expressed and associated with an aggressive phenotype in neuroblastoma." (PMID 33245713, 2020). "LGR5 potentially contributes to stem cell maintenance and self renewal and is indicative of poor survival in high-risk neuroblastoma." (PMID 33245713, 2020). "Our findings show that the stem cell marker Lgr5 is associated with an aggressive phenotype in neuroblastoma." (PMID 26697427, 2015). "Also, studies have demonstrated close associations between Lgr5 and aggressiveness in neuroblastoma cell lines at different stages of treatment, as well as in papillary thyroid cancer." (PMID 31358061, 2019). "Both LGR5 and HOXD10 were associated with cancer cell proliferation and tumor aggressiveness in neuroblastoma." (PMID 33245713, 2020). "Further studies have indicated the involvement of Lgr5 in drug resistance through Wnt signaling in neuroblastoma cell lines." (PMID 31358061, 2019). "In human neuroblastoma, the leucine-rich repeat-containing G-protein coupled receptor 5 (Lgr5) belonging to the R-spondin receptor family, activates ERK1/2, which, together with the wingless/integrated (Wnt)/β-catenin pathway, contributes to tumor growth." (PMID 31117237, 2019). "Our previous work reported high expression of the Wnt modulator LGR5 in a subset of neuroblastoma cell-lines as well as poorly differentiated primary neuroblastomas." (PMID 29505958, 2018). "We also evaluated the effects of Wnt3a/Rspo2 treatment on a third LGR5-positive neuroblastoma cell line, SK-N-AS." (PMID 29505958, 2018). "Taken together these studies indicate a potential role of LGR5 in neuroblastoma cancer stem cell development, warranting further investigation into this protein in this disease." (PMID 26697427, 2015). "To investigate this potential link between elevated LGR5 expression and aggressiveness in neuroblastoma we performed Q-Real Time PCR to determine LGR5 mRNA expression in a panel of 11 neuroblastoma cell lines displaying a wide range of reported aggressiveness." (PMID 26697427, 2015). "Taken together these studies establish LGR5 as a key mediator of proliferative canonical Wnt signalling in neuroblastoma cells." (PMID 26517508, 2015). "In summary, we have shown elevated expression of LGR5 in a subset of neuroblastoma cell lines which are derived from patients at relapse and display an aggressive phenotype." (PMID 26697427, 2015). "Here we report that LGR5 is also highly expressed in a subset of high grade neuroblastomas." (PMID 26517508, 2015). "ERK1/2 signalling is known to play a crucial role in the G1-S phase progression of the cell cycle by negatively regulating the cell cycle inhibitor p27, and consistent with this, reduction of MEK/ERK signalling in LGR5 depleted neuroblastoma cells led to a G1-phase cell cycle arrest." (PMID 26517508, 2015). "Our study therefore characterises new cancer-associated pathways regulated by LGR5, and suggest that targeting of LGR5 may be of therapeutic benefit for neuroblastomas with diverse etiologies, as well as other cancers expressing high LGR5." (PMID 26517508, 2015). "Interestingly, recent studies in mouse models of neuroblastoma and medulloblastoma also discovered increased expression of Lgr5 in the most aggressive tumors." (PMID 23596566, 2013). "In addition, LGR5 was recently shown to promote proliferation of neuroblastoma, another highly aggressive pediatric tumor of neural crest origin." (PMID 23596566, 2013). "Our data suggests that LGR5 plays a key role in not only regulating Wnt signalling, but also MEK/ERK signalling in neuroblastoma cells, thereby regulating proliferation and survival respectively." (PMID 26517508, 2015).
neuroblastoma (continued). "The neuroblastoma cell line SK-NA-S only expresses LGR5 as shown by us and others, and RNA-seq data showed no or little expression of LGR4, LGR6, RNF43, or ZNRF320,35." (PMID 37402772, 2023). "Although these neuroblastoma cell lines underwent apoptosis after short-interfering RNA (siRNA)-mediated LGR5 knockdown, depletion of β-catenin did not affect cell survival." (PMID 29505958, 2018). "Importantly, we also demonstrate novel regulatory properties of LGR5 upstream of MEK/ERK and Akt pro-survival signalling, pathways that are frequently activated in primary neuroblastomas." (PMID 26517508, 2015). "Therefore, in contrast to neuroblastoma cells, LGR5 does not promote the proliferation of ES cells in standard in vitro culture conditions." (PMID 23596566, 2013).